EGFR (epidermal growth factor receptor)
Diseases named in the same sentence as EGFR in open-access papers (continued):
Sharing a sentence is not in itself a finding about the gene and the disease.
lung cancer (continued). "The overexpression of SLUG and SNAIL with the epidermal growth factor receptor (EGFR) mutation in lung cancer cell lines induced the resistance against gefitinib." (PMID 39941895, 2025). "For example, lung cancer tumors with Epidermal Growth Factor Receptor (EGFR) mutations often acquire drug resistance." (PMID 41007213, 2025). "Epidermal growth factor receptor (EGFR) tyrosine kinase inhibitors (TKIs) have exhibited remarkable efficacy against EGFR-mutated lung cancer." (PMID 40713600, 2025). "Targeting EGFR mutations has revolutionized lung cancer treatment through the development of EGFR tyrosine kinase inhibitors (TKIs)." (PMID 40728967, 2025). "Immunotherapy combined with bevacizumab has been shown to improve survival in patients with EGFRm lung cancer after EGFR‐TKI failure but is associated with a high incidence of adverse events." (PMID 39994841, 2025). "We confirmed that an excess of nuclear expression of FTO in EGFR-TKI-resistant NSCLC cells is associated with the development of the EGFR TKI resistance in lung cancer cells." (PMID 40722726, 2025). "A large portion of non–small-cell lung cancer (NSCLC) harbors epidermal growth factor receptor (EGFR) mutations." (PMID 41184230, 2025). "Explore the issues of interest at different stages of the treatment process for patients with EGFR‐mutated non‐small cell lung cancer with brain metastasis during the first‐line EGFR‐TKIs treatment and the subsequent therapy after the failure of EGFR‐TKIs." (PMID 40421655, 2025). "In lung cancer, EGFR mutations are associated with increased PD-L1 activation, promoting immune evasion and creating an immunosuppressive tumor microenvironment (TME) by recruiting tumor-associated macrophages (TAMs) and regulatory T cells (Tregs)." (PMID 40723259, 2025). "There are only a few studies that provide the survival data and analysis of third‐generation targeted drugs in T790M‐negative patients with EGFR‐mutated non‐small cell lung cancer (NSCLC) after progression on first‐ or second‐generation EGFR‐TKIs treatment." (PMID 41399957, 2025). "This study also presents an advanced lung cancer case with meningeal metastasis harboring EGFR exon 21 L858R mutation, which was effectively treated using third-generation TKI osimertinib." (PMID 40696624, 2025). "Research on EGFR mutation prediction of lung cancer based on different machine learning classifiers." (PMID 40708937, 2025). "In this regard, a phase 1/2 clinical trial testing the combination of osimertinib and bevacizumab in 49 patients with EGFR-mutated lung cancer showed promising results, with a PFS at 12 months of 76% and an ORR of 80%." (PMID 40243603, 2025). "Epidermal growth factor receptor (EGFR) mutations account for 15%–25% of non‐small cell lung cancer (NSCLC) cases." (PMID 41308037, 2025). "Liquid biopsy demonstrates a sensitivity of 35%–80% and specificity of 96%–100% for detecting EGFR mutations in lung cancer." (PMID 41244899, 2025). "In recent years, precision treatment for lung cancer has gradually been applied in clinical settings, particularly in patients with EGFR mutations and ALK gene fusions." (PMID 41269529, 2025). "The majority of patients with lung cancer characterized by activating mutations in the epidermal growth factor receptor (EGFR), benefit from therapies entailing tyrosine kinase inhibitors (TKIs)." (PMID 40243603, 2025). "Of note, increased expression of AXL and its ligand GAS6 has been detected in samples from patients with EGFR-mutated lung cancer who acquired resistance to EGFR TKIs." (PMID 40243603, 2025).
lung cancer (continued). "Lung cancer patients co-harboring EGFR Ex19del mutation and MET de novo amplification is extremely uncommon." (PMID 40034596, 2025). "Third‐generation (third‐gen) epidermal growth factor receptor (EGFR) tyrosine kinase inhibitors (TKIs) have revolutionized the management of advanced EGFR‐mutated non‐small cell lung cancer (NSCLC)." (PMID 41211184, 2025). "IL-32 subsequently activates the β5-integrin-Src-Akt pathway to reduce the sensitivity to the third-generation tyrosine kinase inhibitors (TKIs) in EGFR mutated lung cancer patients." (PMID 40248695, 2025). "Through pathway enrichment analysis, we observed 14 pathways associated with lung cancer, with 12 linked to EGFR, 10 to HRAS, and 8 to MAPK8." (PMID 41155483, 2025). "In a silent trial involving 197 patients with lung cancer over a span of 4 months, a fine-tuned pathology foundation model was able to identify the presence of EGFR mutations with high accuracy, potentially preventing further genetic testing in 43% of cases." (PMID 40634781, 2025). "NSCLC comprises approximately 80% to 85% of all lung cancers, with EGFR mutation rates as high as 51.4% in the Asian NSCLC population." (PMID 41383506, 2025). "Therascreen EGFR RGQ Plasma PCR Kit (Qiagen) is a companion test for detection of EGFR mutations in lung cancer patients." (PMID 40787067, 2025). "Given the growing number of long-term survivors of EGFR-mutated lung cancer due to advances in targeted therapy, clinicians should be aware that very late recurrences can occur through atypical metastatic routes such as tumor-to-tumor metastasis." (PMID 41416296, 2025). "At the molecular level, several studies have found that EGFR mutations and ALK rearrangements are less common in COPD-related lung cancer, with EGFR mutations showing an inverse relationship with the severity of airflow limitation." (PMID 40724620, 2025). "In recent years, extensive genomic characterization has revealed various actionable mutations in lung cancer, including epidermal growth factor receptor (EGFR), Kirsten rat sarcoma virus (KRAS), and anaplastic lymphoma kinase (ALK) mutations." (PMID 40647542, 2025). "While LBs have been useful in guiding therapy changes in cancers with known resistance mutations, such as EGFR-driven lung cancer, strong evidence that these adjustments lead to better survival rates is still emerging." (PMID 39934875, 2025). "Of note, HDAC6 is a significant regulator of EGFR signalling activity, in which the knockout of HDAC6 in lung cancer cells caused premature EGFR degradation and trafficking." (PMID 39941046, 2025). "For example, lung cancer progression under the treatment by first- or second-generation EGFR inhibitors requires the analysis of EGFR T790M mutation, which sometimes can be accomplished by ctDNA testing." (PMID 40787067, 2025). "We further demonstrated that combining the PCS with clinical characteristics improved the prediction of EGFR mutation status in lung cancer patients, particularly when incorporating gender and smoking history." (PMID 41415549, 2025). "This review seeks to advance understanding of AI applications in oncology by categorising current algorithmic strategies and summarising recent advances in predicting EGFR mutation status and subtypes in lung cancer." (PMID 40708937, 2025). "EGFR mutations in HCC827, NCI‐H1650, and PC‐9 cells are useful for studying EGFR mutation‐related lung cancer." (PMID 40387186, 2025). "Non‐small cell lung cancer (NSCLC) accounts for more than 80% of all lung cancer cases, in which EGFR mutations are commonly found." (PMID 40855618, 2025). "The missense mutation EGFR L858R in exon 21, which accounts for 41% of all EGFR mutations, has been detected in lung cancer, colorectal cancer, and squamous cell carcinoma of the head and neck." (PMID 40994682, 2025). "Combination of BIBW2992 and ARQ 197 is effective against erlotinib-resistant human lung cancer cells with the EGFR T790M mutation." (PMID 40161336, 2025).
lung cancer (continued). "Real‐world data regarding patients with non‐small cell lung cancer (NSCLC) with EGFR exon 20 insertion (ex20ins) mutations receiving mobocertinib are limited." (PMID 39861957, 2025). "Brain metastasis in lung cancer has become an important reason for the failure of targeted therapy in patients with EGFR mutations." (PMID 40069781, 2025). "For example, there is a positive correlation between EGFR mutations and PD-L1 expression in lung cancer, and EGFR inhibitors act as repressors of PD-L1 transcription." (PMID 40075727, 2025). "Somatic mutation of the epidermal growth factor receptor (EGFR) gene is a major oncogenic driver in nonsmall cell lung cancer (NSCLC)." (PMID 39757012, 2025). "In general, better tumor differentiation correlates with a better prognosis, supporting that EGFR mutation detection aligns with tumor differentiation in determining lung cancer prognosis." (PMID 41378298, 2025). "Targeting EGFR with specific inhibitors has shown clinical efficacy in treating lung cancers with EGFR mutations, making it a critical protein marker in radon-induced carcinogenesis." (PMID 40427695, 2025). "Epidermal growth factor receptor tyrosine kinase inhibitors (EGFR-TKIs) are effective therapies that yield favourable outcomes for patients with lung cancer harbouring activating EGFR mutations." (PMID 40004680, 2025). "Overactivation of the epidermal growth factor receptor (EGFR) is a prevalent genetic mutation in lung cancer, particularly non-small-cell lung cancer (NSCLC)." (PMID 40725000, 2025). "Genetic mutations in the epidermal growth factor receptor (EGFR) are among the most studied genetic mutations in lung cancer." (PMID 41227214, 2025). "EGFR inhibitors have demonstrated great efficacy in tumors dependent on EGFR-activating mutations, such as lung cancer." (PMID 40003864, 2025). "Hypertriglyceridemia was associated with lower risks of overall lung cancer (HR: 0.88 95% CI: 0.83–0.93), adenocarcinoma (0.86 [0.82–0.90]), and EGFR-mutated lung cancer (0.87 [0.83–0.92]) and a greater risk of small cell lung cancer (1.25 [1.11–1.41])." (PMID 39883280, 2025). "The intricate phenomenon of lung cancer metastasis entailed a multitude of contributory factors, encompassing the cancer's pathological classification, epithelial growth factor receptor (EGFR) mutations, therapeutic modalities, and more." (PMID 40650339, 2025). "In non–small cell lung cancer (NSCLC) with EGFR mutations, mTOR expression levels were low to intermediate in most cases (62.5%), while a significant portion (37.5%) exhibited high mTOR expression." (PMID 40754657, 2025). "EGFR inhibitors have been reported to enhance the susceptibility of lung cancer cells to NK‐cell‐mediated lysis." (PMID 40859900, 2025). "used second‐generation sequencing, Sanger sequencing, and quantitative PCR to detect mutations in common lung cancer driver genes such as EGFR and ALK in 24 PACC patients, and the results showed that all patients had no mutations in common driver genes." (PMID 39828507, 2025). "This combination has been evaluated in the phase 1/2 clinical trial TRAEMOS in patients with EGFR-mutated lung cancer that progressed on an EGFR TKI and showed HER2 amplification." (PMID 40243603, 2025). "Briefly, the findings of the current study shed light on a novel molecular mechanism underlying EGFR-TKI-resistant lung cancer, presenting a promising therapeutic strategy." (PMID 39744423, 2025). "Higher LDL was associated with higher risks of developing small cell lung cancer (1.28 [1.08–1.52]) and EGFR-mutated (1.08 [1.02–1.16]) lung cancer." (PMID 39883280, 2025).
lung cancer (continued). "Ten xenografts from lung cancer patients with EGFR mutation (PDX) were used to characterize Hippo signaling after osimertinib treatment." (PMID 40428391, 2025). "Silencing MUC1-C in H1975 cells carrying the EGFR driver mutation L858R/T790M can inhibit lung cancer cell proliferation by suppressing the protein kinase B (Akt) signaling pathway." (PMID 40655139, 2025). "Since 2009, when the EGFR-inhibitor gefitinib was approved in EGFR-mutated lung cancer in Europe, many such personalised therapies have been established and exist now for around one third of all lung cancer patients." (PMID 41387799, 2025). "A significant number of non‐small cell lung cancer (NSCLC) patients in Asia exhibit mutations in the epidermal growth factor receptor (EGFR)." (PMID 40515576, 2025). "Carcinoembryonic antigen (CEA) is a common tumor marker, and a meta-analysis of non-small cell lung cancer (NSCLC) showed that CEA is significantly associated with epidermal growth factor receptor (EGFR) mutations and lung cancer staging." (PMID 41536835, 2025). "Non‐small cell lung cancer patients with EGFR mutation have a high rate of brain metastases, and EGFR tyrosine kinase inhibitors (TKIs) are the principal therapeutic approach." (PMID 40172035, 2025). "PM2.5 exposure has been linked to various mechanisms that initiate and promote lung cancer, particularly through the actions of EGFR and AhR." (PMID 39578555, 2025). "This is the first human‐derived lung cancer brain parenchymal metastasis cell line that both carries a driver gene mutation and demonstrates resistance to third‐generation EGFR‐TKIs." (PMID 40172035, 2025). "EGFR-mutated NSCLC represents a clinically significant subset of lung cancers, characterized by oncogenic driver mutations that promote tumor growth, survival, and progression." (PMID 40733125, 2025). "The discovery of EGFR-activating mutations in a subset of lung cancer patients led to the use of EGFR tyrosine kinase inhibitors (EGFR-TKIs) to treat non-small cell lung cancer (NSCLC) with these specific mutations." (PMID 41358202, 2025). "EGFR is already known as a crucial target for lung cancer treatment, as various structural aberrations and mutations in EGFR can lead to uncontrolled tumor cell proliferation and survival." (PMID 41155483, 2025). "The third generation of epidermal growth factor receptor (EGFR) tyrosine kinase inhibitors (TKIs) is recommended universally as the standard treatment for non‐small cell lung cancer (NSCLC) carrying the EGFR T790M mutation." (PMID 39967842, 2025). "Epidermal growth factor receptor (EGFR)-mutated metastatic non-small cell lung cancer (mNSCLC) is the most common oncogene-addicted lung cancer with a variable global prevalence based on ethnicity." (PMID 40862817, 2025). "The epidermal growth factor receptor (EGFR), a critical receptor tyrosine kinase, plays a pivotal role in lung cancer pathogenesis and progression through its mutational activation." (PMID 41155547, 2025). "It is worth noting that EGFR T790M, primarily associated with acquired resistance in lung cancer after EGFR tyrosine kinase inhibitors therapy, can also be found in a small number of treatment-naive cases." (PMID 40282516, 2025). "EGFR gene mutations in lung cancer are typically linked to adenocarcinoma histology, female gender, non-smoking status, and Asian ethnicity." (PMID 40104451, 2025).
lung cancer (continued). "Hypomethylation of DAPL1 also is associated with the prognosis of the EGFR Del19 mutation subtype in lung cancer patients, and lung cancer patients showing hypomethylation of DAPL1 have significantly longer overall survival times." (PMID 38980592, 2025). "Lung cancer patients with EGFR mutations experience limited benefits from immune checkpoint inhibitors due to a tumour microenvironment that hinders the immune response." (PMID 40149368, 2025). "The third-generation osimertinib (AZD9291) has also been shown to induce apoptosis in lung cancer cells that harbor EGFR mutations." (PMID 40940888, 2025). "After determining a SMARCB1-Driven EGFR expression in lung cancer, we examined if this association had an impact on EGFR-TKI resistance." (PMID 39971779, 2025). "In this case, the EGFR ex19del, typically associated with early lung cancer development, was estimated to have occurred post-WGD, highlighting its potential vulnerability to loss as a resistance mechanism." (PMID 39972134, 2025). "While INI1-deficient lung cancer rarely coexists with EGFR, ALK, or other oncogenic driver mutations, comprehensive genetic profiling (CGP) remains essential for guiding treatment decisions, particularly in advanced-stage patients." (PMID 40291911, 2025). "The advent of epidermal growth factor receptor tyrosine kinase inhibitors (EGFR‐TKIs) has significantly improved survival outcomes in patients with advanced EGFR‐mutated non‐small cell lung cancer (NSCLC)." (PMID 41243674, 2025). "With the development of numerous molecularly targeted drugs, accurately detecting EGFR mutations is crucial for effective treatment of lung cancer." (PMID 39947926, 2025). "Osimertinib is a novel third-generation EGFR TKI that is used in the treatment of EGFR-mutated non–small cell lung cancers." (PMID 40750174, 2025). "For instance, in lung cancer research, organoids have been instrumental in drug screening, leading to the discovery of Manoalide (MA) as an agent that sensitizes KRAS-mutated and osimertinib-resistant lung cancer to EGFR-TKIs." (PMID 40427552, 2025). "EGFR-TKIs represent a significant advancement in lung cancer treatment, demonstrating improved efficacy compared to standard chemotherapy in patients with advanced EGFR mutation-positive NSCLC." (PMID 40370720, 2025). "Central nervous system (CNS) metastases remain a significant challenge in the management of EGFR-variant non–small cell lung cancer (NSCLC)." (PMID 40569623, 2025). "Mutations in the epidermal growth factor receptor (EGFR) gene are established therapeutic targets within lung cancer treatment paradigms, with an overall somatic mutation rate of 30.6% in the Chinese NSCLC population." (PMID 41257744, 2025). "Here, we discovered that a specific isoform of type I protein arginine methyltransferases (PRMT), namely, PRMT1, enables lung cancer cells with EGFR or KRASG12C driver mutations and high STAT1 activity to persist through targeted drug treatments." (PMID 39699269, 2025). "Markers such as vimentin, ZEB, TWIST, and SLUG were seen in EGFR-mutated lung cancer cells upon EGFR TKI (Tyrosine Kinase Inhibitor) therapy, underscoring the role of phenotypic plasticity in therapeutic resistance." (PMID 41304766, 2025). "Improved understanding of the underlying events by which mutant EGFR regulates cellular growth and metabolism is expected to facilitate the development of newer approaches to treat lung cancer." (PMID 40940888, 2025). "For example, a combination of BCL2 inhibitor Navitoclax with a third-generation EGFR inhibitor osimertinib has demonstrated high safety and feasibility in patients with advanced EGFR-mutated lung cancer." (PMID 39735667, 2025). "Retrospective analyses have further revealed that a higher density of tumor-infiltrating CD20+ B cells correlates with better responses to EGFR tyrosine kinase inhibitors (TKIs) in advanced lung cancer patients harboring EGFR mutations." (PMID 40723259, 2025).